MPO (myeloperoxidase)
Diseases named in the same sentence as MPO in open-access papers (continued):
Sharing a sentence is not in itself a finding about the gene and the disease.
granulomatosis with polyangiitis (88 papers, 2001 to 2026). A small-vessel necrotizing vasculitis characterized by the association of inflammation of the vessel wall and peri- and extravascular granulomatosis. "Finally, she was diagnosed with the rare MPO-ANCA-associated granulomatosis with polyangiitis (GPA) superimposed on PSAGN." (PMID 37492611, 2023). "C-ANCA (IIF), proteinase-3 (PR3)-ANCA (ELISA), and myeloperoxidase (MPO)-ANCA (ELISA) in granulomatosis with polyangiitis (GPA), and MPO-ANCA (ELISA) in propylthiouracil-induced vasculitis were IgG1/4-dominant." (PMID 26018403, 2015). "In two case reports of Wegener granulomatosis patients with hepatitis C, one was positive for MPO-ANCA, while another patient had a high titer of PR3-ANCA positivity." (PMID 25161336, 2014). "Myeloperoxidase antibodies are primarily associated with MPA, whereas PR3 antibodies are primarily seen in Wegener's granulomatosis (WG)." (PMID 23533438, 2013). "Although Pr3-ANCA, found in 70 to 90% of patients with Wegener's granulomatosis, is often considered to be a seromarker of this disease, MPO-ANCA has been reported to be predominant in Asian patients." (PMID 21345235, 2011). "Anti-MPO antibodies are characteristic in CSS (associated with p-ANCA), whereas anti-proteinase 3 (PR3) are more specific for Wegener granulomatosis (associated with c-ANCA)." (PMID 23283308, 2008). "Its clinical pattern and histopathology are similar to ocular lesions observed in humans suffering from granulomatosis with polyangiitis (GPA), formerly named Wegener's granulomatosis, where the pathogenesis revolves around anti-neutrophil antibodies (e.g., anti-myeloperoxidase)." (PMID 29061945, 2015). "A second difference in clinical phenotype between patients with MPO-ANCA and PR3-ANCA is the presence of granulomatous inflammation in the latter which is referred to as granulomatosis with polyangiitis." (PMID 37331172, 2023). "Most patients with Wegener's granulomatosis exhibit cANCA with PR3 specificity and 25% exhibit pANCA with MPO specificity." (PMID 18718013, 2008). "Previous studies suggested that monocytes upregulate major histocompatibility complex (MHC) II cell surface receptor human leukocyte antigen receptor (HLA-DR) molecules in granulomatosis with polyangiitis (GPA) patients with proteinase 3 (PR3-) and myeloperoxidase (MPO-) ANCA seropositivity." (PMID 35632410, 2022). "All patients were positive for antibodies to PR-3, the putative antigen for cANCA in Wegener's granulomatosis by Elisa, but none was positive for MPO, the antigen for pANCA." (PMID 23476676, 2013). "The interaction of both ANCA phenotypes (PR3-ANCA and MPO-ANCA) with leukocytes provoked cell activation, which might be involved in the pathogenesis of ANCA-related Wegener's granulomatosis." (PMID 19594951, 2009). "Patients with vasculitis and P-ANCA targeting MPO are most likely suffering from MPA (55–65%), followed by eosinophilic granulomatosis with polyangiitis (EGPA) (30–40%) and GPA (20–30%)." (PMID 34440897, 2021). "She subsequently received a unifying diagnosis of granulomatosis with polyangiitis (GPA) on the basis of these findings as well as high-titer characteristic antibodies (p-ANCA titer 1:640, myeloperoxidase antibody > 30)." (PMID 32131760, 2020). "Systemic small vessel vasculitis with renal involvement is mostly associated with an anti-neutrophil cytoplasmic antibody (ANCA) directed at leukocyte proteinase 3 (PR3-ANCA) and myeloperoxidase (MPO-ANCA), including MPA, GPA, and eosinophilic granulomatosis with polyangiitis (Churg–Strauss)." (PMID 38248794, 2024).
autoimmune disease (87 papers, 2009 to 2025). A disorder resulting from loss of function or tissue destruction of an organ or multiple organs, arising from humoral or cellular immune responses of the individual to their own tissue constituents. "Anti-neutrophil cytoplasmic antibody (ANCA)-associated vasculitis (AAV) is an autoimmune disease targeting myeloperoxidase (MPO)." (PMID 36672249, 2023). "NETs-associated components such as NE or MPO are present in the plasma of individuals with many autoimmune diseases and also in infections, which complicates the specificity of these molecules as biomarkers." (PMID 32765493, 2020). "Anti-neutrophil cytoplasmatic antibody (ANCA)-associated vasculitis (AAV) is an autoimmune disease characterized by the presence of autoantibodies directed against myeloperoxidase (MPO) or Proteinase-3 (PR3) expressed by neutrophils." (PMID 31921121, 2019). "The present study provides a first comprehensive portrait of the gene repertoire of S. aureus isolates from patients suffering from the PR3-ANCA- and MPO-ANCA-associated forms of the autoimmune disease AAV." (PMID 28939882, 2017). "Anti-neutrophil cytoplasmic autoantibody (ANCA)-associated small-vessel vasculitis is an autoimmune disease characterized by autoantibodies directed against neutrophil granule proteins myeloperoxidase (MPO) or proteinase 3 (PR3)." (PMID 27752292, 2016). "Anti-neutrophil cytoplasmic antibodies (ANCA) associated small vessel vasculitis are rare but severe autoimmune diseases which share as central pathogenic element the formation of antibodies against myeloperoxidase (MPO-ANCA) and proteinase 3 (PR3-ANCA)." (PMID 27057255, 2014). "The P-ANCA-positive staining pattern is associated with MPO specificity in vasculitides, while in other autoimmune diseases, it mostly involves unknown autoantigens." (PMID 34440897, 2021). "Additionally, PAD4 inhibitor Cl-amidine or BB-Cl-amidine shows a good therapeutic effect on heart failure-associated autoimmune diseases such as rheumatoid arthritis, lupus erythematosus, MPO-ANCA-associated vasculitis, and Behçet's disease." (PMID 33680285, 2021). "Also, the presence of anti-apoA-I IgG in autoimmune disease has been associated with dysfunctional HDLs, which could be generated by myeloperoxidase-catalyzed apoA-I oxidation." (PMID 25170076, 2014). "Many molecules released in NETs are targeted autoantigens in autoimmune diseases, such as histones, citrulline peptides, and myeloperoxidase." (PMID 39221253, 2024). "Further blood tests revealed markers suggesting an autoimmune disease (IgG4, 139 mg/dL; myeloperoxidase anti-neutrophil cytoplasmic antibody (MPO-ANCA)-positive)." (PMID 38887326, 2024). "It is considered an autoimmune disease, strongly associated with antineutrophil cytoplasmic autoantibody (ΑNCΑ) directed against leukocyte proteinase 3 (PR3) or myeloperoxidase (MPO)." (PMID 39649240, 2024). "One of the tip-top biomarkers of inflammatory and oxidative stress in autoimmune diseases like RA is the serum level of MPO." (PMID 37009006, 2023). "Eosinophils from individuals with T1D have elevated levels of myeloid alpha-defensins and myeloperoxidase, which play a role in inflammatory and autoimmune diseases." (PMID 37780623, 2023). "NETs are a network of histones, elastases, myeloperoxidase (MPO), and cathepsin G released by neutrophils, which can participate in the process of tumors, infections, autoimmune diseases, and other diseases." (PMID 36468006, 2022). "We also discuss novel therapeutic approaches to target MPO activity, expression, or MPO signaling for the treatment of inflammatory and autoimmune diseases." (PMID 36421487, 2022). "It should be noted that both the available literature and the results of our study clearly indicate increased levels of LDG and LDG MPO+ fraction in the PBMC as potential markers among patients with autoimmune disorders." (PMID 35456267, 2022).
autoimmune disease (continued). "According to the literature, elevated MPO levels are observed in a number of autoimmune diseases, including multiple sclerosis and RA." (PMID 35886901, 2022). "As the crucial NET components, DNA, histones, elastase, proteinase 3, myeloperoxidase, and LL-37 are the potential sources of autoantigens participating in the flare-up of autoimmune diseases." (PMID 34572313, 2021). "The up-regulation of VCAM1 occurs in systemic oxidative stress, myeloperoxidase, autoimmune disease and particularly in malignant melanoma." (PMID 32900003, 2020). "A decreased expression of MPO has been suggested to manage these autoimmune disorders by decreasing the inflammatory state." (PMID 32045425, 2020). "Early studies have shown that, as in other autoimmune diseases, PR3-ANCA and MPO-ANCA are associated with alterations in the glycosylation of IgG including a decrease in sialylated and galactosylated structures." (PMID 30818380, 2019). "Loss of tolerance to the neutrophil enzyme myeloperoxidase (MPO) leads to anti-neutrophil cytoplasmic antibody (ANCA)-associated vasculitis (MPO-AAV), an autoimmune disease that can affect multiple tissues but which often involves the kidney." (PMID 31358739, 2019). "ANCA (antineutrophil cytoplasmic antibody)-associated vasculitides (AAV) comprise different types of autoimmune diseases, in which autoantibodies react to proteinase 3 (PR3), or myeloperoxidase (MPO)." (PMID 28077133, 2017). "For comparison purposes, in mouse models of autoimmune diseases, the reported absolute number of antibody secreting cells to myeloperoxidase, nucleolin and dsDNA are higher than 11,000, 17,000 and 33,000 specific cells/spleen, respectively." (PMID 23046563, 2012). "Given that VEGFA, IL2, and MPO all play roles in autoimmune diseases, in this study, kaempferol has been shown to bind well with these molecules, which suggests a potential avenue for therapeutic interventions targeted at these molecular interactions in the context of vitiligo." (PMID 38659590, 2024). "Some studies that correlate sCP and autoantibodies in autoimmune diseases showed that high levels of sCP have been associated with positive autoantibodies (Ab-anti-dsDNA, anti-SSA, anti-Ro60, AchR-Ab, Musk-Ab, LRP4-Ab, levels of MPO and PR3...)." (PMID 38792945, 2024). "In contrast to the often transient positivity of antiphospholipid antibodies, p-ANCA, anti-MPO, and autoantibodies to rheumatoid arthritis and systemic lupus erythematosus may be present for 8 years or more prior to the onset of incident autoimmune disease." (PMID 38390319, 2024). "However, her blood test showed a mild elevation of C-reactive protein level (3.16 mg/dL), with positive IgG4 and myeloperoxidase anti-neutrophil cytoplasmic antibody results, suggesting an autoimmune disease." (PMID 38887326, 2024). "MPO is then entrapped in the extruded materials and drives the production of antineutrophil cytoplasmic antibodies (ANCAs), which have been reported to play a role in the pathogenesis of autoimmune diseases." (PMID 38693312, 2024). "MPO inhibition may therefore enhance inflammation due to autoimmunity and is a further reason for caution in considering MPO inhibition as a treatment for autoimmune disease." (PMID 36154801, 2023). "AAV on the other hand, is a rare autoimmune disease of small and medium blood vessels, caused by the loss of tolerance to neutrophil granule proteins proteinase 3 (PR3) or myeloperoxidase (MPO), and is characterised by the presence of anti-PR3 or anti-MPO autoantibodies, respectively." (PMID 37239388, 2023). "Background and aim: Antineutrophil cytoplasmic antibody (ANCA)-associated vasculitis (AAV) is a rare multisystem autoimmune disease developed by autoantibody production against human neutrophilic granulocytes, including proteinase-3 (PR3) and myeloperoxidase (MPO)." (PMID 36552276, 2022). "MPO-AAV is an autoimmune disease where all these criteria are met." (PMID 34394071, 2021).
autoimmune disease (continued). "Additionally, plasma MPO levels and MPO oxidation products are elevated in patients in autoimmune diseases, such as rheumatoid arthritis and systemic lupus erythematosus, both of which carry an increased risk of CVD." (PMID 33234591, 2021). "Autologous ex vivo-generated regulatory T cells (Tregs) and autoantigen-loaded tolerogenic dendritic cells (DCs) are an appealing tool for the treatment of autoimmune diseases, including MPO-AAV, because they can provide safe, antigen-specific immunosuppression, without posing any risk of rejection." (PMID 34394071, 2021). "In addition, myeloperoxidase (MPO), an enzyme abundantly expressed by neutrophils and promotes inflammation, is also involved in autoimmune disorders (multiple sclerosis, rheumatoid arthritis)." (PMID 32045425, 2020). "Antineutrophil cytoplasmic antibody (ANCA)-associated vasculitis (AAV) is a rare autoimmune disease (AID) with the hallmarks of chronic inflammation within the blood vessels and the production of ANCAs directed against myeloperoxidase (MPO) and proteinase 3 (PR3)." (PMID 31694209, 2019). "Anti-neutrophil cytoplasmic autoantibody (ANCA)-associated vasculitis (AAV) constitute a group of autoimmune diseases characterized by pauci-immune necrotizing small-vessel inflammation and by the production autoantibodies against proteinase 3 (PR3-ANCA) and myeloperoxidase (MPO-ANCA)." (PMID 30356862, 2018). "Franck and colleagues demonstrated that MSCs inhibit NET-MPO even after the release of NETs from activated neutrophils, indicating that MSCs may have therapeutic potential to treat autoimmune diseases or inflammatory conditions that are driven by the catalytic activity of MPO." (PMID 36293108, 2022). "However, high levels of MPO correlate with the prevalence of certain autoimmune diseases." (PMID 33916434, 2021). "Finally, latest research shows that MPO may not only be pivotal for innate immunity, but seems to have a potential role in adaptive immunity and autoimmune diseases." (PMID 32899838, 2020). "Overall, these studies indicate that the net impact of MPO on disease development depends on the balance between its local injurious effects in the target organ and inhibitory effects on adaptive immunity in secondary lymphoid tissue and that this balance varies in different autoimmune diseases." (PMID 26904693, 2016). "Among all autoimmune diseases, anti-GBM patients are most prone to develop anti-neutrophil cytoplasmic antibody (ANCA) positivity, typically in the form of anti-myeloperoxidase (MPO) antibodies." (PMID 37781380, 2023). "In the case reported here, we excluded autoimmune disease because all ANA, MPO-ANCA, and PR3-ANCA values were within normal ranges." (PMID 35980544, 2022). "NETs can break self-tolerance by being a source of autoantigens for autoantibodies found in autoimmune diseases, such as anti-citrullinated protein antibodies (ACPAs) in RA, anti-dsDNA in SLE and anti-myeloperoxidase and anti-protein 3 in AAV." (PMID 32276504, 2020). "For instance, systemic lupus erythematosus (SLE) is an autoimmune disease that is characterised by high levels of autoantibodies against proteinase-3 (PR3) and myeloperoxidase (MPO), proteins that are highly expressed and sequestered within neutrophil granules." (PMID 38965211, 2024). "A number of our asthma patients had positive anti-MPO antibodies in our experimental assays, and clinical ANCA results, but did not have other aspects of EGPA to support a diagnosis of the systemic, vasculitic autoimmune disease." (PMID 37334358, 2023). "Since we found associations between oxidative stress markers (MPO and GSH) and CD, it is essential to note that such an association was not previously observed in autoimmune diseases." (PMID 38093175, 2023).
autoimmune disease (continued). "As for many other autoimmune diseases, current treatments for MPO-AAV are only partially effective, but are harmful and non-specific, thus causing significant serious side effects in many patients which lead to considerable complications and death." (PMID 34394071, 2021). "The results of this study indicate that, although MPO represents the most common P-ANCA specificity for MPA, autoantibodies to additional novel neutrophilic self-antigens are likely present in P-ANCA-positive autoimmune disease patients." (PMID 34440897, 2021). "Although autoimmune disease was a differential diagnosis in this patient, anti-MAC antibody, anti-nuclear antibody, MPO-ANCA, and PR3-ANCA tests yielded negative results, ultimately resulting in a diagnosis of aortitis attributed to G-CSF administration." (PMID 40860786, 2025). "Although clinical trials using CAR-Treg and TCR-Treg therapies in MPO-AAV have not yet commenced, both in vitro and in vivo studies in other autoimmune diseases support their feasibility and therapeutic potential." (PMID 41256853, 2025). "Unlike SLE, AAV is an autoimmune disease lacking IC formation, while ANCA binding to the membrane-bound myeloperoxidase on resident neutrophils can bring about intra-pulmonary NETosis in such patients." (PMID 37700342, 2023). "In many autoimmune diseases, a negative feedback loop between tissue damage and inflammation exists, where MAP3K8 promotes myeloperoxidase activity, ROS production, and recruitment of neutrophils and macrophages, causing tissue damage." (PMID 30463908, 2018).